CHRM3 (cholinergic receptor muscarinic 3)
Diseases named in the same sentence as CHRM3 in open-access papers (continued):
Sharing a sentence is not in itself a finding about the gene and the disease.
Hypertension (3 papers, 2017 to 2023). The presence of chronic increased pressure in the systemic arterial system. "Prior evidence shows that variants in the CHRM3 gene are associated with hypertension, obesity-related traits, and platelet count." (PMID 28820441, 2017). "rs12118522, mapped to CHRM3, is associated with hypertension and body fat distribution." (PMID 37669986, 2023). "Thus, it is the functional impact of Chrm3 signaling that determines the hypertension pathogenesis, not any of the non-coding rodent SNPs around the Chrm3 codons and the non-existent human GWAS SNP." (PMID 32702059, 2020).
lung carcinoma (3 papers, 2021 to 2025). "We also found that AMP treatment significantly inhibited lung cancer cell proliferation, migration, and invasion via downregulating CHRM3." (PMID 40718823, 2025). "Our recombinant overexpression lentivirus significantly increased the expression of CHRM3 in the three lung cancer cell lines compared to the lentivirus control." (PMID 40718823, 2025). "First, we assessed the expression of CHRM3 in six lung cancer cell lines (NCI-H460, NCI-H446, NCI-H520, A549, NCI-H1299, and NCI-H1975)." (PMID 40718823, 2025). "AMP treatment inhibits the proliferation, migration, and invasion of lung cancer via the CHRM3/PI3K/AKT and CHRM3/MAPK pathways, thus exerting antitumor activity." (PMID 40718823, 2025). "Three lung cancer cell lines (A549, NCI-H1299, and NCI-H520) with baseline CHRM3 expression were infected with recombinant CHRM3-overexpression or -knockdown lentivirus." (PMID 40718823, 2025). "Next, we established lung cancer cells (A549, NCI-H1299, and NCI-H520) with stable overexpression of CHRM3 by infection with recombinant CHRM3-overexpression lentivirus and cultured under puromycin for one month." (PMID 40718823, 2025). "Here, we found that AMP treatment inhibits the proliferation, migration, and invasion of lung cancer via the CHRM3/PI3K/AKT and CHRM3/MAPK pathways, thus exerting antitumor activity." (PMID 40718823, 2025). "Lung cancer cell lines (A549, NCI-H1299, and NCI-H520) with stable overexpression or knockdown of CHRM3 were established by infection with recombinant lentivirus and selected under puromycin for one month." (PMID 40718823, 2025). "Both the RT-qPCR and western blot data showed that CHRM3 was highly expressed in the SCLC-SCC NCI-H520 cell line, moderately expressed in the adenocarcinoma cell lines A549 and NCI-H1299, but not expressed in the other lung cancer cell lines." (PMID 40718823, 2025).
pancreatic cancer (3 papers, 2021 to 2024). "For instance, high expression levels of CHRM3 have been found to predict poor prognosis in patients with pancreatic cancer, suggesting CHRM3 as a potential prognostic marker." (PMID 39225813, 2024).
xerostomia (3 papers, 2020 to 2024). Dryness of the mouth resulting from reduced salivary secretion. "Furthermore, CHRM3 (encoding muscarinic acetylcholine receptor 3 (M3R)) is the target of M3R agonist pilocarpine, used in glaucoma, ocular hypertension and xerostomia, and of antagonists revefenacin and aclidinium bromide, used in chronic obstructive pulmonary disease treatment." (PMID 39566559, 2024). "In PCS/ME/CFS patients, the secretomotor symptoms (dry eyes, dry mouth) correlated negatively with levels of AABs against AGTR1, EDNRA, ADRA1A, ADRB1/2, and CHRM3 (black bars)." (PMID 36238301, 2022). "Similarly, the negative correlation of the secretomotor symptoms (dry eyes, dry mouth) with levels of AAB against vasoregulatory receptors AGTR1, EDNRA, ADRA1A, ADRB1/2, and CHRM3 indicate a vascular mechanism." (PMID 36238301, 2022).
Alzheimer disease (2 papers, 2018 to 2025). A progressive, neurodegenerative disease characterized by loss of function and death of nerve cells in several areas of the brain leading to loss of cognitive function such as memory and language. "The aim of this study was to investigate the association of the polymerphic variation in CHRM2 gene (rs6962027) and CHRM3 gene (rs7511970) in relation to early- and late-onset of Alzheimer’s disease." (PMID 30090216, 2018).
bladder cancer (2 papers, 2016 to 2019). "Five haplotypes (GTTAT, ATTGT, GCTAC, ACTAC, and ACCAC) were found significantly associated with low CHRM3 mRNA level and contributed to increased susceptibility of bladder cancer in Kaohsiung city after rigid 10000 consecutive permutation tests." (PMID 28053981, 2016). "Evidence from our genetic and functional studies suggested that some risk haplotypes were significantly associated with low CHRM3 mRNA level and contributed to increased susceptibility of bladder cancer in Kaohsiung city." (PMID 28053981, 2016). "Our study attempted to delineate whether genetic variants of CHRM3 contribute to bladder cancer in Chinese Han population in south Taiwan." (PMID 28053981, 2016). "Thus, we attempted to delineate the genetic association of CHRM3 genotypes and bladder cancer." (PMID 28053981, 2016). "Although the association of bladder cancer and CHRM3 is significant, we could not completely exclude a possibility of false-positives because of small sample size or other factors (e.g., confounders with other medical conditions and adjustment of other risk factors)." (PMID 28053981, 2016). "However, no solid evidence showed the genetic effect of CHRM3 gene polymorphism on bladder cancer." (PMID 28053981, 2016).
breast carcinoma (2 papers, 2015 to 2022). "However, CHRM3 gene expression showed an increased risk in breast cancer (BRCA-LumA); M4 receptor gene expression showed an increased risk in BRCA-Basal, but a decreased risk in BRCA-Her2 adjusted by stage clinical factor." (PMID 35565451, 2022).
endometrial carcinoma (2 papers, 2019 to 2023). A malignant tumor arising from the epithelium that lines the cavity of the uterine body. "CHRM3 (cholinergic receptor muscarinic 3) is a novel gene in ESCC, but its expression has been associated with poor prognosis in endometrial carcinoma." (PMID 37641095, 2023).
myopia (2 papers, 2013 to 2024). "CHRM3 and TGFβ1 have been implicated in the pathogenesis of myopia in Taiwanese individuals, while a high-myopia GWAS of Asian datasets identified the SNP rs6885224 in the CTNND2 gene on chromosome 5p15.2 as being associated with myopia." (PMID 39062192, 2024). "Following lens treatment, lens-treated eyes had developed myopia after 6 weeks, whereas, with the exception of M2 and M3 (Chrm3) mutant mice, untreated control eyes had not." (PMID 23649821, 2013).
renal cell carcinoma (2 papers, 2015 to 2025). "Molecular docking findings indicate that the environmental endocrine-disrupting chemical BPA specifically interacts with key targets essential for the function of renal cell carcinoma cells, including CHRM3, GABBR1, CCR4, KCNN4, PRKCE, CYP2C9, HPGD, and FASN." (PMID 41301871, 2025).
benign prostatic hypertrophy (1 paper, 2019). "CHRM3 is overexpressed in bladders of adults with benign prostatic hypertrophy, most likely a compensatory response to anatomic bladder outflow obstruction." (PMID 31441039, 2019).
bladder disorder (1 paper, 2019). "This is the first independent report of biallelic variants in CHRM3 in a family with a rare serious bladder disorder associated with mydriasis and provides important evidence of this association." (PMID 31441039, 2019).
colorectal adenocarcinoma (1 paper, 2023). The most common type of colorectal carcinoma. "In an unbiased analysis, we found that in contrast to CHRM3, expression of CHRM1 was significantly downregulated in human colorectal adenocarcinomas." (PMID 37835460, 2023).
gastric tumors (1 paper, 2020). "Expression of NGF and YAP was also associated with advanced stages of gastric tumors, which further substantiates the critical roles of Chrm3-NGF and Chrm3-YAP axes in tumor pathology." (PMID 32477953, 2020).
intestinal cancer (1 paper, 2020). "Besides, inhibition of Chrm3 was shown to attenuate small intestinal neoplasia, further confirming the therapeutic utility of Chrm3 blockers in intestinal cancers." (PMID 32477953, 2020).
intestinal tumor (1 paper, 2014). "In mice, ablating Chrm3, the gene encoding M3R, robustly attenuates intestinal tumor formation." (PMID 24694019, 2014).
lung fibrosis (1 paper, 2024). "Mutations in the CHRM3, HLA-DRB1, PLAU, and SETD2 genes are closely linked to the pathogenesis of pulmonary fibrosis." (PMID 38575860, 2024).
metastatic colorectal cancer (1 paper, 2020). "In metastatic colorectal cancer, the inadvertent activation of evolutionarily methylation-silenced genes MET, RAB3IP and CHRM3 proto-oncogenes have been identified." (PMID 32905102, 2020).
Mydriasis (1 paper, 2019). Abnormal dilatation of the iris. "Previously, we reported brothers in a family affected by a congenital prune belly‐like syndrome with mydriasis due to homozygous CHRM3 frameshift variants." (PMID 31441039, 2019). "The report of this second family provides independent evidence that biallelic variants in CHRM3 result in severe bladder voiding dysfunction which on the basis of the families described to date is associated with mydriasis and is more severe, resulting in early lethality, in males." (PMID 31441039, 2019). "Although dilated pupils are present in all affected individuals reported to date with biallelic CHRM3 variants indicating that this is a core feature of the phenotype, the association of bladder dysfunction with mydriasis is not exclusive to individuals with CHRM3 variants." (PMID 31441039, 2019).
Nausea (1 paper, 2025). A sensation of unease in the stomach together with an urge to vomit. "CHRM3, whose-related nausea responded to ondansetron, is expressed at higher levels in the upper gastrointestinal tract compared to TACR1, whose-related nausea did not respond to ondansetron, consistent with the access of ondansetron on CHRM3 in the upper gastrointestinal tract outside the BBB." (PMID 40691854, 2025). "Thus, ondansetron may suppress CHRM3-related nausea predominantly outside the BBB." (PMID 40691854, 2025). "This indicates that AA carriers of CHRM3 rs2165870 exhibited a preventive effect of ondansetron against nausea, whereas CC carriers of TACR1 rs3755468 exhibited only a limited preventive effect of ondansetron against nausea." (PMID 40691854, 2025).
pemphigus vulgaris (1 paper, 2022). Pemphigus is a group of chronic autoimmune skin diseases characterized by blister formations on the outer layer of the skin and the mucous membranes. "Patients with pemphigus vulgaris feature some of the same alterations in adhesion, epidermal stem cell proliferation, and differentiation as observed in the experimental model of Chrm3 inactivation." (PMID 35870560, 2022). "This study also sheds new light on the pathophysiology of pemphigus vulgaris where some patients develop autoantibodies inactivating CHRM3 through receptor desensitization." (PMID 35870560, 2022). "Similar to the epidermal changes in Chrm3−/− mice, anti-CHRM3 pemphigus autoantibodies upregulate K5 and downregulate K10 in mice—findings that are mirrored in the epidermis of patients with pemphigus vulgaris." (PMID 35870560, 2022).
psychotic disorder (1 paper, 2019). An abnormal condition of the mind that involves a loss of contact with reality. "CHRM3 was co-expressed with three psychosis risk genes (GABAG2, CHRNA4, and HRH3) in the thalamus and other human brain tissues and mouse GABAergic neurons." (PMID 31740666, 2019).
small cell lung carcinoma (1 paper, 2020). Small cell lung cancer (SCLC) is a highly aggressive malignant neoplasm, accounting for 10-15% of lung cancer cases, characterized byrapid growth, and early metastasis. "Chrm3 was also shown to promote Small Cell Lung Carcinoma (SCLC) by activating MAPK and Akt signals." (PMID 32477953, 2020).
stomach adenocarcinoma (1 paper, 2016). "To explore the signaling downstream of ACh, we analyzed stomach adenocarcinoma data from the TCGA dataset and discovered that the level of AMPK phosphorylated at Thr 172 is positively correlated with expression of CHRM3 mRNA, which encodes M3R." (PMID 26919111, 2016).
urofacial syndrome (1 paper, 2022). "Several monogenic causes of other congenital bladder outflow obstruction disorders have been described including BNC2 in urethral stenosis; FLNA in syndromic urethral anomalies; HPSE2 and LRIG2 in urofacial syndrome; CHRM3 in prune-belly like syndrome; and MYOCD in megabladder." (PMID 36124557, 2022).
tumor (31 papers, 2011 to 2026). "As a GPCR regulating smooth muscle contraction and glandular secretion, CHRM3 drives tumor progression in multiple cancers." (PMID 41301871, 2025). "The genetic silencing of CHRM3 reduced tumor growth by 50%, whereas radiotherapy paradoxically amplified neuron–tumor connectivity, a vulnerability exploited by combining radiation with AMPA receptor inhibition, which synergistically suppressed growth." (PMID 40243726, 2025). "In patient-derived GBM organoids (GBOs) and brain slices, tumor cells engaged in synaptic-like interactions with glutamatergic and cholinergic neurons, with cholinergic signaling via the CHRM3 accelerating proliferation." (PMID 40243726, 2025). "Our work highlights the relevance of the cholinergic system in the tumor microenvironment, mainly through CHRM3." (PMID 41516199, 2025). "Evaluation of primary tumor single-cell/single-nucleus datasets revealed the muscarinic receptor CHRM3 as the most highly expressed cholinergic receptor gene across various CNS tumors, including DMG." (PMID 40541184, 2025). "CHRM3 knockdown led to impaired cortical tumor growth, suggesting acetylcholine is a key mediator in neuron-tumor communication." (PMID 39798116, 2025). "It has been reported that BAs can induce oncogenesis and tumor progression via CHRM3-mediated pathways." (PMID 36919835, 2023). "Specifically in PCa, miR‐30e exhibited a tumor suppressor role by targeting genes such as CHRM3, CTHRC1 and genes in MAPK signaling pathway." (PMID 35612714, 2022). "Tumor measurements revealed 28 and 74% reduction, respectively, in tumor number and size for Chrm3-/- compared to WT mice (P < 0.05 and P < 0.005, respectively), consistent with our previous work." (PMID 24694019, 2014). "As anticipated from our previous work, tumor number and size as well as tumor cell proliferation measured by Ki67 staining were greatly attenuated in AOM-treated Chrm3-/- compared to WT mice." (PMID 24694019, 2014). "Compared to AOM-treated WT mice, AOM-treated Chrm3 knockout mice had 40% and 60% reductions in tumor number and size, respectively." (PMID 24694019, 2014). "At the 20-week end-point, only colons from Chrm3-/- mice had reduced tumor burden compared to WT mice." (PMID 24694019, 2014). "We were further surprised to observe that combined Chrm3 and Chrm1 knockout mitigated reductions in tumor number and size observed with Chrm3 knockout alone." (PMID 24694019, 2014). "This is consistent with our previous observation that in azoxymethane-treated mice, genetic ablation of Chrm3 attenuates both tumor size and tumor number, including the number of adenocarcinomas." (PMID 23617763, 2013). "Additionally, the inhibition or genetic ablation of the muscarinic acetylcholine receptor 3 (CHRM3) yields effects akin to those observed with vagal denervation, highlighting its significant influence on tumor dynamics." (PMID 41601691, 2026). "For instance, co-administration with EGFR-targeted TKIs or immune checkpoint inhibitors may yield additive or synergistic tumor control by simultaneously targeting CHRM3-driven proliferation and enhancing apoptotic or immune-mediated clearance." (PMID 40718823, 2025). "In this work, we also demonstrate that TSLP increased CHRM3 expression in the U251 cell line, enhancing tumor malignancy, probably by further promoting the complex interaction of GBM cells with the brain microenvironment and their tendency to aggressively infiltrate normal brain tissue." (PMID 41516199, 2025). "On the other hand, the genetic deletion of AChR Chrm3 on CD8+ T cells reduced HCC tumor growth." (PMID 39200261, 2024). "The mice with CHRM3-KD exhibited significantly decelerated tumor progression." (PMID 37744266, 2023). "The acetylcholine (ACh) released by PNS is its main neurotransmitter, which can act on the cholinergic receptor muscarinic 3 (CHRM3), thereby enhancing the activity of the Wnt signaling pathway and promoting the proliferation and migration of tumor cells." (PMID 40761255, 2025).
tumor (continued). "In xenograft mice bearing A549 tumors, CHRM3 knockdown showed little inhibition on tumor growth, but AMP treatment inhibited the tumor growth." (PMID 40718823, 2025). "Cholinergic receptor muscarinic 3 (CHRM3), a member of the G protein-coupled receptor family, was shown to inhibit tumor cell viability, colony formation, migration, and invasion, and promote apoptosis when silenced." (PMID 37700319, 2023). "Key pathways activated in neoplasias by BAs are regulated by nuclear receptors, FXR, CAR, SHP, PXR, LXR and VDR and other membrane receptors such as S1PR2, TGR5, CHRM2 and CHRM3." (PMID 35429253, 2022). "The expressions of CHRM3.AS2, MIR205HG, and LINC00661 from the TCGA and GEO databases were remarkably upregulated in tumor tissues compared with those in normal tissues." (PMID 34926294, 2021). "In our study,the expressions of CHRM3.AS2, MIR205HG, and LINC00661 were significantly increased in tumor tissues of CCA patients, further verifying the prognostic prediction value of the established signatures for CCA." (PMID 34926294, 2021). "The unanticipated findings regarding the impact of Chrm3 and Chrm1 knockout on AOM-induced colon neoplasia provided an opportunity to explore M3R-regulated changes in tumor gene expression." (PMID 24694019, 2014). "At the molecular level, ATXN8OS sponged a tumor-suppressive miR-424-5p, thereby activating key oncogenes such as EYA1, DACH1, and CHRM3, which could be suppressed by Rg3 treatment." (PMID 33477683, 2021). "Ingenuity Pathway Analysis of this data set did not reveal involvement of a known pathway to explain tumor attenuation in AOM-treated Chrm3-/- compared to WT mice (data not shown)." (PMID 24694019, 2014). "CHRM3 was frequently and strongly upregulated in tumor lesions compared to adjacent tissue in three cohorts, using cirrhotic or non-cirrhotic tissue as non-tumor controls." (PMID 39717507, 2025). "Based on our previous findings regarding the interplay of M1R and M3R in gastric function, we hypothesized that compared to the effects of Chrm3 gene ablation alone, concurrent ablation of Chrm3 and Chrm1 might further attenuate, or even abolish, AOM-induced tumor formation." (PMID 24694019, 2014). "While the expression of many AChRs was not altered in comparison to the cellular tumor, we did find significant upregulations in the expression of CHRNA7, CHRNB2, CHRM1, and CHRM3 in these areas." (PMID 31590360, 2019).